PTX3 (pentraxin 3)
Diseases named in the same sentence as PTX3 in open-access papers (continued):
Sharing a sentence is not in itself a finding about the gene and the disease.
cancer (continued). "It is well known that PTX3 may play a pivotal role in the regulation of Complement cascade activation and the literature provides several evidences of an insidious relationship between Complement activation and cancer in terms of cellular proliferation and angiogenesis." (PMID 33110136, 2020). "PTX3 is involved in CEBPD-induced acquired chemoresistance, stemness, and metastasis/invasion of cancer cells." (PMID 30740360, 2019). "Long pentraxin-3 (PTX3) is a component of the innate immunity with pleiotropic functions in the regulation of immune response, tissue remodeling, and cancer progression." (PMID 31480336, 2019). "For example, Ptx3, upregulated in MLL-TINT only, was increased in histologically benign prostate epithelial cells adjacent to cancer in patients." (PMID 28472073, 2017). "Herein, we found elevated gene expression of PTX3 in malignant and metastatic HNSCC tissues according to the cancer microarray database (Oncomine 4.0)." (PMID 25797258, 2015). "Additionally, PTX3 surpasses other members of the pentraxin family, such as NP1, NP2, and PTX4, in terms of its prognostic significance across a broad range of cancers." (PMID 39594709, 2024). "Interestingly, with the UALCAN database, PTX3 protein expression was increased in KIRC and GBM, while it was decreased in other cancers." (PMID 36139597, 2022). "In this study, our initial exploration showed that PTX3 was related to ICIs, as well as TMB, MSI, and NEO s cores, which might predict immunotherapy efficacy for cancers." (PMID 36139597, 2022). "It was shown that PTX3 expression was positively correlated with most chemokines, chemokine receptors, major histocompatibility complex (MHC) genes, and immunostimulatory genes in most human cancers, except TGCT." (PMID 36139597, 2022). "In line with this, researchers have investigated the involvement of pentraxin-3 (PTX-3) in cellular proliferation and immune escape in various types of cancers, although it has not been clearly elucidated." (PMID 36499628, 2022). "Increased PTX-3, PCT and CRP levels in the current study, inflammation may be one of the key promoters in the development and progression of cancer." (PMID 33776564, 2021). "PTX3 was originally identified as the inducible genes of IL-1 and TNF-α, which are widely involved in the regulation of inflammatory diseases, such as pneumonia, cystitis and cancer-related inflammation." (PMID 31957804, 2020). "PTX3 has been shown to play non-redundant functions in various physiopathological conditions, including angiogenesis and cancer." (PMID 30443492, 2018). "In order to set the basis for the development of novel PTX3-derived FGF2 antagonists with potential therapeutic implications, the PTX3-derived pentapeptide ARPCA was characterized in preclinical models of FGF-dependent angiogenesis and cancer." (PMID 30349543, 2018). "PTX3 is secreted by a diverse range of cell types, including immune cells (e.g., dendritic cells, monocytes, and macrophages) and non-immune cells such as cancer cells, typically upon stimulation by pro-inflammatory mediators." (PMID 41479916, 2025). "Although PTX3 engages commonly recognized signaling pathways, such as TNF-α, NF-κB, FGF, and PI3K/AKT, it can exert paradoxical effects in different cellular contexts, either promoting or inhibiting the proliferation, migration, invasion, and metastasis of cancer cells." (PMID 41479916, 2025). "However, we discovered that the administration of recombinant PTX3 protein had no discernible effect on the proliferation of either cancer cells or fibroblasts." (PMID 38243273, 2024). "In PDAC tissues, PTX3 was previously found expressed by mesenchymal stellate cells in the stroma; however, in our study, PTX3 was overexpressed in cultured KRAS-transduced epithelial pancreatic cells, demonstrating that cancer cells may also produce PTX3 upon KRAS transformation." (PMID 35681634, 2022). "Many researchers agree that the role of PTX3 in cancer has not been yet fully established." (PMID 36290747, 2022).
cancer (continued). "However, in comparison with other types of cancer, PTX-3 serum levels were not different among patients with long or short survival rates." (PMID 36499628, 2022). "Researches showed editing role in the pathogenesis of cancer and indicated its relation with mediators such as tumour necrosis factor-α (TNF-α), soluble TNF-related apoptosis-inducing ligand (sTRAIL), interleukin-6 (IL-6), pentraxin-3 (PTX-3), procalcitonin (PCT), and Creactive protein (CRP) levels." (PMID 33776564, 2021). "However, despite its ability to act as a natural FGF trap, no data are available about a possible involvement of PTX3 in primary cilium length determination under physiological and pathological conditions, including cancer." (PMID 32630309, 2020). "Based on the results obtained in ptx3b zebrafish morphants and the well-known impact of PTX3 on FGF-dependent tumors, we decided to investigate whether the modulation of PTX3 expression may affect primary cilia in FGF-dependent cancer cells." (PMID 32630309, 2020). "EGF induced cancer cell migration in parental but not PTX3-knockdown cells." (PMID 25797258, 2015). "It is tempting to postulate that PTX3 may be up-regulated by inflammatory conditions, and may play a unique role in the process of osteolytic cancer cells rather than osteoblastic cancer cells, but further evidence is required to confirm this speculation." (PMID 24457902, 2014). "Thus, PTX3 is a potent candidate marker of inflammation, including cancer-related inflammation: however, the precise role of PTX3 in cancer progression has not been elucidated." (PMID 24457902, 2014). "Although our current results suggest that CD44 is a novel PTX3 receptor and that the PTX3/CD44 complex does indeed play a vital role in the promotion of metastasis/invasion and stemness of cancer cells, we cannot rule out other potent PTX3 receptors and their involvement in tumourigenesis." (PMID 35090088, 2022).
cardiovascular disease (73 papers, 2008 to 2026). "High plasma PTX3 levels are linked to an increased risk of cardiovascular diseases, according to several clinical studies." (PMID 40332236, 2025). "Human studies have suggested that obese individuals have elevated plasma PTX3 levels and increased expression of PTX3 in visceral adipose tissue, which have been linked with cardiovascular diseases." (PMID 34035808, 2021). "On the other hand, in the observational arm of the same study, adipose pentraxin-3 mRNA was increased in CKD patients with cardiovascular disease but the association disappeared after adjustment." (PMID 29316724, 2018). "Other clinical studies indicated that PTX3 levels associate with cardiovascular disease and all-cause death among apparently healthy older individuals and patients with CHD." (PMID 24705587, 2014). "Recently, notable results were described in PTX3-deficient murine experiments; the elevation of PTX3 during cardiovascular diseases has recently been postulated to be a compensatory response to protect the body from inflammation." (PMID 25587447, 2014). "PTX3, on the other hand, is an interesting new plasma marker, because it is associated with cardiovascular disease severity, restenosis and has prognostic value in patients with ST-elevation myocardial infarction." (PMID 24060373, 2013). "In order to determine if radiotherapy is a risk factor for cardiovascular disease, we chose to study PTX3." (PMID 24060373, 2013). "Contribution of PTX3 and C-reactive protein level or the combination of the two to the risk prediction of prevalent cardiovascular disease." (PMID 22319633, 2012). "Addition of PTX3 to a model including standard vascular risk factors improved its predictive accuracy for cardiovascular disease and the overall performance was better than that observed for hsCRP." (PMID 22319633, 2012). "In the population based Bruneck Study, PTX3 level was independently associated with prevalent cardiovascular diseases (multivariable odds ratio [95%CI] 3.09 [1.65–5.79]; P<0.001)." (PMID 22319633, 2012). "The prototypic long pentraxin PTX3 is also associated with cardiovascular disease independently of CRP." (PMID 20920344, 2010). "Furthermore, PTX3 has been linked to the advancement of cardiovascular diseases (CVD) in a number of investigations." (PMID 35522573, 2022). "PTX3 is an inflammatory marker and it is associated with cardiovascular disease risk factors." (PMID 26566413, 2015). "A similar observation was confirmed in the Cardiovascular Health Study where PTX3 was showed to be independently associated with increased risk of all-cause death and cardiovascular-disease-(CVD-) related mortality (also after adjusting for all major cardio-metabolic risk factors)." (PMID 23690668, 2013). "When compared to CRP, PTX3 predicted prevalent cardiovascular disease better, had fewer associations with other vascular risk conditions and may be more specific for vascular wall inflammation." (PMID 22319633, 2012). "PTX3, a member of the pentraxin superfamily of acute phase proteins, is considered to be a novel immunoinflammatory marker that has been reported to associate with cardiometabolic risk factors and to predict adverse outcomes in individuals with cardiovascular disease." (PMID 23626755, 2013). "As a multifunctional protein, PTX3 has been shown to be actively involved in cardiovascular diseases, tumorigenesis, and inflammatory disorders." (PMID 40362562, 2025). "Elevated pentraxin 3 levels have been reported in cardiovascular diseases, autoimmune disorders, and various inflammatory conditions." (PMID 40095687, 2025). "Attention has been drawn to the hypothesis that PTX-3 can modulate inflammation, and increased PTX-3 levels in patients with cardiovascular risk may reflect a physiologically protective mechanism associated with the immunoinflammatory response observed in various cardiovascular diseases." (PMID 38510866, 2024).
cardiovascular disease (continued). "The role of PTX3 in health and diseases has been widely documented, especially in inflammation, oxidative stress, immune response, cardiovascular diseases, and metabolic diseases." (PMID 39296904, 2024). "On the contrary, in the presence of HF and other cardiovascular diseases, PTX3 is expressed in multiple cell types, such as adipose and cardiac cells, in the heart." (PMID 38397422, 2024). "Osteopontin and pentraxin-3 have a two-faced phenotype and dual character that have frequently been reported in cardiovascular disease." (PMID 38581060, 2024). "Elevated levels of PTX3 have been found in the course of sepsis and bacteraemia, cardiovascular diseases, and coronary artery disease." (PMID 35330038, 2022). "PTX3 correlates negatively with GFR and is associated with cardiovascular disease, inflammation, and protein-energy wasting." (PMID 34064989, 2021). "The role of PTX3 levels in metabolic and cardiovascular diseases development in PCOS should also be examined." (PMID 32934654, 2020). "“Novel” serum biomarkers like ST2 and Pentraxin-3 (Ptx-3) have recently emerged as a potentially useful tool for improving the assessment of cardiovascular disease." (PMID 32085400, 2020). "Pentraxin-3 (PTX-3) has been well-studied in inflammatory diseases, particularly in cardiovascular diseases associated with vascular endothelial dysfunction." (PMID 32670996, 2020). "It has been suggested that PTX-3 plays dual roles, both protective and harmful, in the development and the progression of a cardiovascular disease." (PMID 32670996, 2020). "PTX3 plays a crucial role in host defense and is increasingly expressed during septic shock, cardiovascular diseases, obstructive pulmonary disease and atherosclerosis." (PMID 30796272, 2019). "Several studies have suggested PTX3 as a therapeutic tool for cardiovascular disorders although contradictory findings leave this point unresolved." (PMID 27559355, 2016). "The aim of this paper will be to discuss the experimental and clinical relevance of PTX3 in cardiovascular diseases." (PMID 23690668, 2013). "In the present study we observed a consistently sustained upregulation of the novel cardiovascular disease marker PTX3 in all human irradiated conduit arteries and veins." (PMID 24060373, 2013). "In the last decade, the presence of PTX3 was detected in the myocardium and in the vasculature under different pathological conditions which was paralleled by the observation of increased plasma PTX3 levels in patients with cardiovascular disorders." (PMID 23690668, 2013). "One potentially useful biomarker for cardiovascular disease is PTX3, and many studies have recently examined this protein in clinical situations." (PMID 22347626, 2012). "As PTX3 has promise as a biomarker for cardiovascular disease, we have recently determined the normal physiological concentration of this protein." (PMID 22347626, 2012). "Several evidences link PTX3 and cardiovascular diseases: PTX3 production by smooth muscle cells stimulated by atherogenic LDL, localization in atherosclerotic lesions, and high expression level observed in the heart during inflammatory reactions." (PMID 21776288, 2011). "These recent studies suggest unique functional properties of PTX3 in the pathogenesis of cardiovascular diseases." (PMID 21048961, 2010). "Measurement of plasma PTX3 levels is likely to be useful for targeted therapies for primary prevention of cardiovascular disease." (PMID 19014569, 2008). "Current data shows that PTX3 could become a useful predictive biomarker in cardiovascular diseases or even a potential therapeutic target." (PMID 40573228, 2025). "The increase in PTX3 levels following aerobic exercise may represent a protective physiological response against cardiovascular diseases, involving complement activation, opsonization, angiogenesis, and tissue repair." (PMID 41562853, 2025).
cardiovascular disease (continued). "In addition to being a multipurpose soluble pattern recognition molecule that is essential for innate immunity and the inflammatory response, pentraxin 3 (PTX3) is now known to be a distinct marker of cardiovascular disease." (PMID 40911117, 2025). "Pentraxin-3 (PTX-3), an acute-phase protein belonging to the PTX family, is produced in response to pro-inflammatory factors, and elevated levels promote the formation of blood clots, which is significantly associated with cardiovascular diseases." (PMID 41281269, 2025). "The presence of PTX3 was detected in the myocardium in various pathological conditions, which was parallel to the observation of increased levels of PTX3 in plasma in patients with cardiovascular disorders." (PMID 35566693, 2022). "PTX-3 may have a different site-specific function, which could explain the pro-inflammatory and the anti-inflammatory roles of PTX-3 in cardiovascular diseases." (PMID 32670996, 2020). "Concordantly, studies have shown the association of inflammatory markers especially CRP which is among the GPS score variables, interleukin-6 (IL-6), tumor necrosis factor alpha, pentraxin 3 and neutrophil-to-lymphocyte ratio with poor prognosis in cardiovascular diseases." (PMID 31096693, 2019). "Therefore, the emergence of inflammatory factors PTX3 and hs-CRP also provide new ideas for the early prevention and treatment of GDM and the prediction of long-term cardiovascular disease risk." (PMID 31721795, 2019). "Epigenetic modulation of PTX3 gene in cardiovascular diseases is increasingly emerging." (PMID 27559355, 2016). "Thus, this specific production pattern of PTX3, explains its involvement in multiple cardiovascular disorders." (PMID 27559355, 2016). "Further investigations may elucidate the specific role of PTX3 in various contexts of cardiovascular disease." (PMID 24705587, 2014). "In this context, PTX3 was chosen to serve as biomarker for cardiovascular disease." (PMID 24060373, 2013). "The expression and involvement of PTX3 in cardiovascular diseases are discussed in this paper, along with the characteristics of PTX3 that make it a suitable biomarker; namely, that the physiological concentration is known and it is independent of other risk factors." (PMID 22347626, 2012). "Finally, preliminary data suggest PTX3 level to be superior to hsCRP in predicting prevalent cardiovascular disease." (PMID 22319633, 2012). "PTX3 is, in contrast with CRP, highly conserved between mice and humans and might therefore be associated with cardiovascular disease in COPD." (PMID 20920344, 2010). "Therefore, PTX3 may be an effective target point for the prevention and treatment of cardiovascular disease in red pandas." (PMID 35898935, 2022). "In addition, ascending PTX3 in cardiovascular disease may show protective physiological response, which might be related to the severity of the disease." (PMID 33746606, 2021). "PTX3 and hs-CRP may be related to the pathogenesis of GDM, and they are significantly increased in the second trimester, which provides a new idea for early prevention and treatment of GDM and risk prediction of long-term cardiovascular diseases." (PMID 31721795, 2019). "However, several pathological conditions, such as cardiovascular diseases and kidney diseases induce increased PTX3 circulating levels and must be taken into consideration as potential confounding factors in the stratification of septic patients with these underlying conditions." (PMID 31031772, 2019). "However, most studies linking Pentraxin-3 to negative outcomes are clinical observational and associate the molecule to endothelial dysfunction, cardiovascular disease, protein energy wasting and in a study focusing on the elderly, also incident CKD." (PMID 29316724, 2018).